CST3 (cystatin C)
Diseases named in the same sentence as CST3 in open-access papers (continued):
Sharing a sentence is not in itself a finding about the gene and the disease.
kidney disease (continued). "Therefore, patients with renal disease present high levels of cystatin C, which may inhibit proteases that promote the degradation of atherosclerotic plaque." (PMID 29694626, 2018). "Cystatin C may be the most sensitive indicator of CMB severity among the renal disease markers." (PMID 24925313, 2014). "Thus, an increased cystatin C concentration could identify early deviations in GFR and may play a sensitive indicator of “preclinical” renal disease, which may thus be associated with mortality." (PMID 24967238, 2013). "Since creatinine-based eGFR is not reliable above 60 mL/min/1.73 m2, cystatin C may be superior in detecting an association with inflammation in subjects with mild to moderate kidney disease." (PMID 18681974, 2008). "The biomarker model (sTNFR1, sTNFR2, cystatin C, eGFR) measured at Day 90 discriminated those with MAKE365 with an AUC of 0.79 [95% confidence interval (CI) 0.68-0.91], and kidney disease progression with AUC 0.79 (95% CI 0.67-0.91)." (PMID 42094028, 2026). "However, the significant association between cystatin C and C-reactive protein (a marker for inflammation) does not imply a causal relationship, as inflammation plays an important role in the early stages of kidney diseases." (PMID 37663661, 2023). "In seven other studies, the kidney outcomes measured included serum creatinine, serum cystatin C, eGFR, the prevalence of CKD or symptoms of kidney disease based on ICD-9." (PMID 35479765, 2022). "According to the Kidney Disease: Improving Global Outcomes (KDIGO) guideline for the other cystatin C indications such as borderline eGFRcr between 45 and 74 ml/min/1.73 m2 or persons at high risk of CKD, more subjects might require to be tested for cystatin C." (PMID 36530922, 2022). "Urine concentrations of cystatin-C and TWEAK were significantly higher in patients with active renal disease than in healthy controls (P= 0.0014, 0.0005, respectively)." (PMID 35720325, 2022). "Studies have demonstrated that serum cystatin C is a sensitive biomarker for detecting changes in GFR and identifying preclinical renal disease, particularly in diabetic patients with a normal serum creatinine concentration." (PMID 33401560, 2021). "Moreover, Odden at al. showed that Cystatin C concentration increases significantly with age, even in the absence of risk factors for kidney disease and that particularly in elderly patients, cystatin C is a better marker for estimate GFR, compared with creatinine." (PMID 32784471, 2020). "Patients with renal disease were found to have higher serum levels of prealbumin, anti-scl-70, RF, anti-extractable nuclear antigen (ENA), anti-SSB, anti-SM, urea, creatinine, cystatin C, α1-microglobulin (α1-MG), serum β2-microglobulin, and other molecules." (PMID 33042142, 2020). "Serum Cystatin C and urinary NAG provide an early and sensitive marker of occult tubular dysfunction resulting from renal disease or nephrotoxic damage." (PMID 27648206, 2016). "Glomerular filtration rates (GFRs) were estimated using serum creatinine–based [Modification of Diet in Renal Disease (MDRD) and Cockroft-Gault and cystatin C based (Larsson) equations." (PMID 25961558, 2015). "Additionally, our results were supported by other recent studies which reported that both visceral and subcutaneous adiposity were associated with kidney disease, as defined by only cystatin C based equations, but not when defined using the creatinine based equations." (PMID 24876964, 2014). "Renal function was estimated using Cockcroft-Gault formula, Modification of Diet in Renal Disease (MDRD) and cystatin C-estimated glomerular filtration rate (GFR)." (PMID 21223578, 2011). "In most cases the glomerular filtration rate (GFR) is estimated based on serum creatinine and the Modification of Diet in Renal Disease (MDRD) formula, but cystatin C-estimated GFR is being used increasingly." (PMID 21067456, 2011).
kidney disease (continued). "Previously we have shown that a four-biomarker model of soluble tumour necrosis factor receptor-1 and -2 (sTNFR1, sTNFR2), cystatin C and estimated glomerular filtration rate (eGFR) measured 90 days after AKI performed well in predicting subsequent kidney disease progression." (PMID 42094028, 2026). "Unlike creatinine, cystatin C is not affected by muscle mass, which supports its use as a marker of kidney disease in chronic illness with muscle wasting." (PMID 39791983, 2025). "The high negative predictive value means 91% of patients who have a negative (normal GFR as defined by Cystatin C based eGFR) do not have kidney disease." (PMID 38654183, 2024). "We applied Modification of Diet in Renal Disease (MDRD) formula to calculate eGFR for DKD classification; nevertheless, other methods include (CKD-EPI)creatinine, CKD-EPIcystatin C and CKD-EPIcreatinine–cystatin C equations were calculated as well." (PMID 38349886, 2024). "This means the chances of having a negative test (normal GFR) as determined by Cystatin C based eGFR in a subject with renal disease is only 9%." (PMID 38654183, 2024). "Alternative serum factors, such as cystatin C, may thus be helpful to better estimate glomerular filtration rate in ALS patients with suspected kidney disease." (PMID 37801095, 2024). "The vast majority (>90%) of those patients remaining in CKD stage 1 or 2 after recalculating the eGFR using cystatin C were indeed not diagnosed to suffer from primary or secondary renal disease." (PMID 38132491, 2023). "For example, there was no biological variables such as relevant biomarkers of cystatin C, neutrophil gelatinase-associated lipocalin (NGAL, a new marker of kidney disease), etc., in addition to urine albumin-to-creatinine ratio (UACR)." (PMID 35314714, 2022). "Therefore, in recent years, the Kidney Disease: Improving Global Outcomes (KDIGO) and ADA proposed to use the eGFR calculation formula based on serum creatinine and cystatin C, such as CKD-EPI cystatin C formula and CKD-EPI creatinine-cystatin C formula." (PMID 34895352, 2021). "GFR was based on the CKD Epidemiology Collaboration (CKD-EPI) equations (CKD-EPI creatinine (CKD-EPIcr), CKD-EPI cystatin C (CKD-EPIcys), CKD-EPI creatinine-cystatins (CKD-EPIcr-cys)), Modification of Diet in Renal Disease (MDRD) and Cockcroft-Gault formula (CGF)." (PMID 32854641, 2020). "Third, there was no data with cystatin C or combined creatinine-cystatin C-based eGFR, which is more accurate than the Modification of Diet in Renal Disease Study Group (MDRD) based eGFR27." (PMID 31792292, 2019). "Widely available markers, serum cystatin C, urine IgG, transferrin, and NGAL, may help in early assessment of kidney disease in T2DM patients; however, large prospective studies are needed to confirm the conclusion." (PMID 30158836, 2018). "Our findings indicate that the widely available markers such as serum cystatin C, urine IgG, transferrin, and NGAL may help in early assessment of kidney disease in T2DM patients, although large prospective studies are needed to confirm the conclusion." (PMID 30158836, 2018). "And some new renal disease markers, such as cystatin C and lipoprotein phospholipase A2, are not included." (PMID 29925312, 2018). "Recently, cystatin C was proposed as a potential marker for kidney disease but this has not been studied thoroughly in Malaysia." (PMID 25946939, 2015). "In healthy rats without kidney disease, cystatin C was expressed in a granular cytoplasmatic fashion in cells of the proximal tubule." (PMID 25310591, 2014). "Serum cystatin C was assumed to be a sensitive indicator of“pre-clinical” renal disease which can not be detected by eGFR based on serum creatinine." (PMID 22978689, 2012). "Third, while albuminuria was used to define early kidney disease, other markers of kidney function, such as cystatin C, were not included, which may have provided a more comprehensive assessment of kidney health." (PMID 40587684, 2025).
kidney disease (continued). "In our case, cystatin C helped rule out kidney disease and prevented unnecessary investigations." (PMID 41194845, 2025). "The CoV for scan–rescan repeatability of cortical T1 mapping reported here for volunteers without renal disease (ranging from 1.9% to 2.8%) are comparable to or lower than those reported for commonly used kidney function tests, such as serum cystatin C or creatinine." (PMID 39468402, 2025). "Thus, in conjunction with other renal tests we can use Cystatin C based eGFR as a confirmatory test to rule out kidney disease." (PMID 38654183, 2024). "This pilot-study identified several serum biomarkers that could be used to predict progression of T2D to more serious kidney disease: namely, midkine, sTNFR1 and 2, H-FABP and Cystatin C. Our results warrant confirmation in a longitudinal study using a larger patient cohort." (PMID 35846341, 2022). "Further research on changes of other biomarkers, such as cystatin c and NGAL,other pathological and functional aspects of the kidney, and also details of apoptoticpathways are necessary to confidently consider the clinical application of hEnSCs for thetreatment of renal diseases." (PMID 34837685, 2021). "Neither plasma cystatin C nor GFR (cystatin C clearance) showed signs of overt renal disease." (PMID 24667016, 2014). "The estimation of serum Cystatin-C could be helpful in the diagnosis of PE, reflecting a different feature of the disease as a stable indicator of an altered filtration process and may also prove valuable for the monitoring of GFR in renal disease in pregnancy and in PE." (PMID 28781906, 2017). "Moreover, a post hoc analysis of the “Modification of Diet and Renal Disease” study (the origin of eGFR based on serum creatinine) has shown that dietary protein reduced the change in creatinine, but did not significantly affect cystatin C changes." (PMID 24852037, 2014).
cardiovascular disease (123 papers, 2007 to 2025). "As many of the non-GFR determinants of increased cystatin C are shared risk factors for cardiovascular disease, it is plausible that previous studies have found cystatin C-based eGFR show strong associations with cardiovascular outcomes." (PMID 41209168, 2025). "eGFR using cystatin C levels has been shown to have a stronger correlation with future risk of cardiovascular disease and death than eGFRcreat." (PMID 40034484, 2024). "Recent research suggests a positive correlation of circulatory IL-6 and Cystatin-C concentrations; increased Cystatin-C levels predict an increased likelihood of cardiovascular disease, renal impairment and all-cause mortality." (PMID 37062827, 2023). "The Serum creatinine/cystatin C ratio (Cr/CysC ratio) is anemerging alternative index for muscle mass loss, a risk factor for cardiovasculardiseases (CVDs)." (PMID 39076382, 2023). "Kidney function is usually estimated from serum creatinine level, whereas an alternative glomerular filtration marker (cystatin C level) associates more closely with future risk of cardiovascular disease (CVD) and mortality." (PMID 36282503, 2022). "Does estimation of kidney function by cystatin C level improve risk-stratification for cardiovascular disease and mortality?" (PMID 36282503, 2022). "High levels of serum creatinine and reduced eGFR have also been demonstrated to be indicative of progressive cardiovascular disease among diabetic patients, and increased levels of cystatin C have been associated with the development of cardiovascular events." (PMID 29694626, 2018). "The general theory of why elevated cystatin C is associated with increased cardiovascular risk is that it represents impaired renal function, which in turn contributes to increased risk of cardiovascular disease." (PMID 26057752, 2015). "Strong and independent associations between plasma concentration of cystatin C and risk of cardiovascular disease (CVD) suggests causal involvement of cystatin C." (PMID 26057752, 2015). "Increased plasma level of cystatin C is associated with increased risk of cardiovascular disease (CVD) and mortality in the elderly and in different patient populations." (PMID 26057752, 2015). "The serum levels of creatinine, cystatin C, and urinary albumin excretion which are factors significantly associated with cardiovascular disease were evaluated as indicators of kidney function." (PMID 24678413, 2014). "In other studies, the stronger association between cystatin C with mortality and cardiovascular disease was ascribed to other variables, as older age and higher BMI." (PMID 24977136, 2014). "Cystatin C is independently associated with cardiovascular disease after adjustment for major cardiovascular risk factors." (PMID 22152087, 2011). "Patients with elevated levels of cystatin C are at higher risk of developing cardiovascular diseases." (PMID 22152087, 2011). "Cystatin C is independently associated with cardiovascular disease and our objective was to investigate the relation between this novel biomarker and standardized bed rest." (PMID 22152087, 2011). "Cystatin C level is associated with the future risk of cardiovascular disease and mortality." (PMID 39685972, 2024). "Cystatin C-based GFR has also been shown to be a stronger predictor of cardiovascular disease outcomes which may mediate this association." (PMID 35477353, 2022). "Like the general population, higher levels of cystatin C was associated with a two-fold increase in the likelihood of cardiovascular disease (odds ratio (OR) 2.65), although the 95% confidence interval was wide, reflecting significant uncertainty in the result (0.84 to 8.37)." (PMID 32255469, 2020). "This confounding association makes it difficult to establish whether cystatin-C is a true measure of renal function or rather a reflection of cardiovascular disease risk factors." (PMID 30563479, 2018).
cardiovascular disease (continued). "However, further longitudinal studies that directly assess the development of cardiovascular disease are still necessary to confirm the superiority of cystatin C to predict this risk in comparison to other renal biomarkers." (PMID 29694626, 2018). "The exploration of the possible mechanisms underlying cystatin C and cardiovascular disease may provide more approaches to prevent and treat macrovascular disease in the future." (PMID 23843968, 2013). "Further investigations may lead to a better understanding of the mechanisms underlying these associations, as well as the role of these associations in predicting cardiovascular disease in subjects with elevated cystatin C." (PMID 21269477, 2011). "Plasma cystatin C has been extensively characterized as a peripheral biomarker for kidney function and as a prognostic indicator of the risk of morbidity and mortality relating to cardiovascular disease." (PMID 21151566, 2010). "Existing evidences suggests that cystatin C-based estimation of CKD offers superior prognostic value and more accurate prediction of cardiovascular diseases, cardiovascular death, and all-cause mortality than creatinine-based estimation." (PMID 40983592, 2025). "Cystatin C-based eGFR demonstrates greater sensitivity and specificity for assessing cardiovascular disease and mortality risks, particularly in mild CKD." (PMID 40983592, 2025). "The elevation of cystatin C has been observed in patients with cardiovascular diseases including pre-capillary PH." (PMID 37633906, 2023). "This is particularly evident in cases of mortality and cardiovascular disease, where the superiority of cystatin C is most pronounced among individuals with GFRs greater than 45 mL/min/1.73 m2." (PMID 37509111, 2023). "In recent years, the relationship between cystatin C and cardiovascular diseases has been increasingly confirmed." (PMID 37817071, 2023). "Cystatin C is a biomarker of kidney function and for predicting new-onset or deteriorating cardiovascular disease." (PMID 35846341, 2022). "Cystatin C (CST3, encoded by CST3) is a cysteine protease inhibitor that regulates cathepsins involving in atherosclerotic lesions of cardiovascular disease." (PMID 35478846, 2022). "The advantage of equations that comprise cystatin C includes greater prognostic values for mortality and cardiovascular disease events and is most apparent among individuals with GFR of 45–59 mL/min/1.73 m2." (PMID 34943527, 2021). "Cystatin C is a potent cysteine protease inhibitor that plays an important role in various biological processes including cancer, cardiovascular diseases and neurodegenerative diseases." (PMID 34440840, 2021). "Beyond its use in the estimation of kidney function, cystatin C-based eGFR has been shown to be a superior predictor of cardiovascular disease (CVD) and mortality when compared to serum creatinine-based eGFR6." (PMID 32255469, 2020). "Cystatin-C has been proven to inhibit cysteine proteases and lead to neuro-degeneration and cardiovascular diseases." (PMID 29026428, 2017). "Established as biomarkers of AKI, both NGAL and cystatin C have been well explored in cardiovascular diseases beyond confines of nephrology." (PMID 25853556, 2015). "Serum cystatin C levels can be used to predict morbidity and mortality in patients with cardiovascular disease." (PMID 25591903, 2015). "Rather, the authors concluded that serum cystatin C was correlated with cardiovascular disease in overweight subjects." (PMID 26185688, 2015). "Net reclassification improvement of eGFR categories for all-cause mortality and cardiovascular disease hospitalization and/or mortality using CKD-EPI cystatin C equation compared with CKD-EPI creatinine equation." (PMID 25265151, 2014). "With these aspects in mind, we will discuss the clinical utility of fibrinogen, vitamin D, and cystatin C in cardiovascular disease management." (PMID 23630624, 2013).